WT1 (WT1 transcription factor)
Diseases named in the same sentence as WT1 in open-access papers (continued):
Sharing a sentence is not in itself a finding about the gene and the disease.
tumor (continued). "This normal tissue sample, a pool from 5 different healthy donors, expressed higher WT1 levels than any of the tumour samples, but lacked both the exon 1A and intron 5 isoforms." (PMID 28345629, 2017). "We tested the robustness of the approach by evaluating six different amounts of tumor DNA, ranging from 60 ng to 6 pg, and searched for both the tumor-specific fusion event and for the non-rearranged WT1 gene." (PMID 27863505, 2016). "Immunohistochemically, the tumor cells express cytokeratin, calretinin, D2-40, thrombomodulin, and nuclear WT1 but are negative for Ber-EP4, CEA, CD15, and CD34." (PMID 27293940, 2016). "Two other mesothelial related markers, CK 5/6 and WT1, are also helpful both in diagnosis and in differential diagnosis from nonmesothelial lesions, even in cases of an infracted tumor." (PMID 28003830, 2016). "The frequency of WT1 deletions was significantly higher in WTs that later relapse than in the group without relapse (21 versus 6.4 %); one tumor from a patient who relapsed was found to carry both WTX and WT1 deletions." (PMID 26913079, 2016). "We also demonstrated that primed CD11c+ CD8+ T cells exert an effector phenotype and contribute to tumor regression in mouse; in two tumor-implant models, EG7(OVA) and C1498(WT1), CD11c+ CD8+ T cell expansion is feasible accompanied with potent therapeutic efficacy." (PMID 27619885, 2016). "This cell line is cytogenetically stable and can be grown indefinitely representing a valuable tool to study the effect of a complete lack of WT1 in tumor cells." (PMID 27213811, 2016). "Two tumours with MLLT1 mutations also had CTNNB1 mutations; no MLLT1-mutant tumours had accompanying WT1, WTX, DROSHA, DGCR8, SIX1, or SIX2 mutations." (PMID 26635203, 2015). "Cell cycle/cell division enrichment (orange nodes) is also biased towards the WT1-wild-type tumours, although not exclusively." (PMID 26035382, 2015). "Perhaps most relevant to the clinical setting, immunization of mice with WT1 peptides was shown to induce anti-tumor activity without inhibiting engraftment of normal CD34+ hematopoietic progenitor cells." (PMID 25699052, 2015). "Furthermore, seven paired samples of tumor and normal tissues of seven non-small cell lung cancer (NSCLC) was examined for the Ex4a(+)WT1 isoform." (PMID 26090994, 2015). "Most remarkable is the presence of classic cancer hallmark GO terms in the WT1-wild-type tumour/Pax8+/CreWt1 conditional sets but absence of these in the Nes-Cre-driven mutants/WT1-mutant tumours." (PMID 26035382, 2015). "In conclusion, our study provides support for a model wherein WT1 can influence tumor growth by regulating angiogenesis independent of tumor oxygenation." (PMID 24810959, 2014). "Tumor cells are negative for CK, WT1 and desmin, and the stroma is rich in nerve fiber network, with ganglion cell differentiation commonly observed." (PMID 25037705, 2014). "In conclusion, the present study showed that in MPNST, at least in vitro, WT1 acts as an oncogene rather than a tumor suppressor." (PMID 25474318, 2014). "WT1 expression was related to higher FNCLCC histologic grade and AJCC tumor stage." (PMID 25026998, 2014). "In fact, more recently, there have been some evidences about that BL is not a true neoplasm but rather a lymphatic vascular malformation by reason of the absence of Wilms tumor 1 (WT-1) expression." (PMID 25358645, 2014).
tumor (continued). "To determine whether WT1 affected NSCLC progression in vivo, we established a xenograft tumor model using Balb/cnu/nu mice." (PMID 23936312, 2013). "Wilms’ Tumour antigen 1 (WT1) is a well characterised tumour antigen overexpressed by haematological and certain non-haematological malignancies." (PMID 23840834, 2013). "Besides enhanced tumor trafficking activity, we attempted to examine the impact of the co-introduced CCR2-CCL2 axis on WT1-responsiveness itself in double-transfected effector cells." (PMID 23441216, 2013). "The majority of WT is wild type for WT1 and CTNNB1 and are found with perilobar nephrogenic rests; the initiating mutation in these tumours is not clear." (PMID 23239670, 2013). "Furthermore, we successfully provided experimental evidence that the suppression of tumor growth mediated by CCR2 and WT1-siTCR double-transfected effector T cells was more effective than that mediated by WT1-siTCR single-transfected cells." (PMID 23441216, 2013). "Consequently when STAT3 was activated, WT1 functioned as a tumor suppressor, but when STAT3 was de-activated, WT1 functioned as an oncoprotein." (PMID 23936312, 2013). "For example, The stable introduction of the WT1 -/- isoform into G401, a kidney-derived tumor cell line that does not express endogenous WT1, alters cellular morphology and reduces tumor formation in athymic nude mice." (PMID 22244202, 2012). "One tumor, GOS 206, showed exclusive loss of only the distal Chr11:pter-17449758 region, which did not include the WT1 locus." (PMID 21544195, 2011). "With the exception of the DU145 cells, WT1 and EGR1 expression levels were consistent with the frozen paired tissue samples examined; that is, WT1 expression was elevated (p < 0.05) and EGR1 expression reduced (p < 0.001) in tumor cell lines relative to RWPE-1 prostate epithelial cells." (PMID 20426842, 2010). "In the majority of invasive stage T3 tumors, WT1 expression levels are higher (2.0 fold or greater) in tumor than in non-neoplastic tissues." (PMID 20426842, 2010). "Conversely, in the majority of localized stage T2 tumors WT1 expression levels are lower in tumor than non-neoplastic tissues." (PMID 20426842, 2010). "Further analysis of WT1 protein identified expression in 65% of tumor samples and, more importantly, the absence of expression in non-neoplastic and BPH samples." (PMID 20426842, 2010). "In paired tumor and non-neoplastic tissue, WT1 expression was elevated in 70% of high-grade tumors examined." (PMID 20426842, 2010). "In addition they reported that RQ-PCR showed a tumor-specific expression of the antigens BAGE, G250 and hTERT, as well as highly tumor-restricted expression for RHAMM, PRAME and WT1." (PMID 19662193, 2007). "Tumor markers ordered included: CK7, CK20, TTF1, ER, PR, Calretinin, WT1, CA 125, BRST-2, and CEA." (PMID 18036260, 2007). "Only chemotherapy response and residual tumor showed significant difference between WT1 staining and no WT1 staining patients." (PMID 16606472, 2006). "tumor cells exhibited positivity for vimentin, NSE, AE1/AE3 and WT1." (PMID 15777480, 2005). "In addiction to consistent WT1 expression, the typical serosal involvement in DSRCT has raised the possibility that this tumor might be a blastematous tumour derived of primitive mesothelium." (PMID 15777480, 2005). "tumor cells exhibited positivity for vimentin, EMA, NSE, chomogranin A, AE1/AE3 and WT1." (PMID 15777480, 2005). "Apart from a few zinc-finger proteins, such as WT1, BCL11A, Evi9, EWS, TLS, GLI, and CTCF, the function of the majority of zinc-finger proteins in tumour occurrence and development is unknown." (PMID 15354214, 2004).
tumor (continued). "Immunohistochemistry showed that tumor cells were CAM5.2 (+), AE1/3 (+), Ber-EP4 (–), EMA (+), CD45 (+), NSE (+), Synaptophysin (–), Chromogranin A (–), CD56 (+), NKX2.2 (–), Vimentin (+), GFAP (–), S-100 (–), Desmin (–), SMA (–), WT1 (–), MyoD1 (–), Myogenin (–)." (PMID 40034204, 2025). "T cells binding one of the WT1 epitopes with low affinity, might not be activated properly and thus fail to initiate tumor destruction." (PMID 39259326, 2025). "For example, in a child with a WT1 germline predisposition and bilateral tumours at diagnosis (PD48701), a metastatic lung recurrence shared no somatic mutations with the primary tumour, and had segregated early in development, as evidenced by mutually exclusive mosaic mutations." (PMID 39665570, 2025). "Moreover, WT1 expression in tissue biopsies significantly correlated with the expression of the viral latent oncoprotein LANA, and inversely correlated with T cells within the tumor and surrounding stromal tissue." (PMID 38190392, 2024). "In contrast, WT1-specific CD8+ T cells from DSP-7888 Emulsion-treated mice secreted 2.5-fold more IFN-γ when incubated with anti-PD-1 vs isotype control antibody in the absence of tumor cells." (PMID 36138335, 2023). "As proven above, WT1 exerted oncogenic activities by promoting NSCLC cell proliferation, survival and invasion, thus we suspected that its inhibitor, miR-498-5p, might possess the opposite tumour suppressive roles." (PMID 37667197, 2023). "Finally, we proved that miR-498-5p was a potent tumour suppressor in NSCLC by suppressing cell proliferation, survival and invasion, while WT1 restoration could in turn disrupt this suppression both in vitro and in vivo." (PMID 37667197, 2023). "Moreover, many unique mutations were only found in CSF samples, but not in the tumor tissue and plasma samples, which includes FH mutation, SETD2 mutation, WT1 mutation, CDKN2A mutation, CDKN2B mutation." (PMID 36937524, 2023). "WT1 negativity suggested that the tumor was not derived from Sertoli cells." (PMID 37843278, 2023). "Here, we investigate the hypothesis that the Wilms tumour gene product (WT1), which is expressed in intra-abdominal WAT but not in subcutaneous WAT and BAT, suppresses a thermogenic program in white fat cells." (PMID 34846543, 2022). "Out of the 56 cases evaluated, 49 demonstrated negative WT1 staining within the tumor tissue." (PMID 35453662, 2022). "Noteworthy is the fact that, in all five cases, the tumor tissue was negative for WT1 staining." (PMID 35453662, 2022). "Although meticulous evaluation of nuclear details may help solve this differential diagnosis, an IHC panel that includes CK7, racemase(AMACR), WT1 and CD57 is also useful for definitive diagnosis, with special attention being paid to tumor transitional areas (low grade to high grade cellularity)." (PMID 35453662, 2022). "In addition, PDPN was found to interact functionally with the tumor promoters Kdr/Vegfr2 and Wt1 which were induced by Src, but not affected by contact normalization." (PMID 35177067, 2022).
tumor (continued). "Interestingly, although more than a quarter of evaluated cases showed massive inflammatory infiltrates, visibly on HE-stained samples, the WT1-positive tumors showed very little to no morphological infiltration of immune cells into the tumor stroma." (PMID 35453662, 2022). "Another encountered particularity, referring strictly to intratumoral endothelial cells, is the fact that, in 3 of the 56 cases analyzed, these cells manifested positive WT1 nuclear staining, while tumor cell immunoreactivity for WT1 was negative for all of the three cases." (PMID 35453662, 2022). "WT1 shows exceptionally low to absent expression in normal tissues while it is highly expressed in a wide range of malignant neoplasms with its key role being in regulating tumor cell proliferation." (PMID 34638574, 2021). "In addition, WT1 was ranked as the No. 1 antigen among 75 tumor antigens by the National Cancer Institute pilot project developing a priority list of tumor vaccine target tumor-associated antigens." (PMID 34589578, 2021). "The 36-38 kDa isoform of WT1 may be involved in the progression of the neoplasm due to the lack of the repression domain." (PMID 34845427, 2021). "We show that immunisation of HHDII/DR1 mice with HAGE- and WT1-ImmunoBody® DNA vaccines in a prime-boost regime in two different flanks induce significant IFN-γ release by splenocytes from treated mice, and a significant level of cytotoxicity against tumour targets expressing HAGE/WT1 in vitro." (PMID 34262856, 2021). "We previously identified a WT1 protein-derived 16-mer HLA class II peptide, WT1332 (KRYFKLSHLQMHSRKH), which can elicit WT1332-specific CD4+ T-cell responses, and demonstrated that this WT1332 peptide was endogenously generated from the WT1 protein in WT1-expressing tumor cells." (PMID 30430205, 2019). "To verify whether dysfunctional T cells are enriched in tumor-specificities at this early time point, we took advantage of MHC dextramers to identify tumor-specific (WT1, PRAME, or EZH2) and control viral-specific (cytomegalovirus-CMV) CD8+ T cells from patients." (PMID 30911002, 2019). "TDLU epithelial cells within the tumours were also noted to be Wt1-positive (not shown)." (PMID 30374123, 2018). "The number of cells expressing WT1 was not different in ER-positive and ER-negative tumours." (PMID 30374123, 2018). "However, ER-positive tumours had a higher number of CD31-positive cells, WT1/CD31 co-expressing cells, total blood vessels, and WT1-positive blood vessels (whether expressed as total number or percentage)." (PMID 30374123, 2018). "Tumors generated from all MPM cultures were strongly positive for calretinin, confirming that the in-vitro growth did not modify the epithelioid subtype phenotype of the tumor of origin, while the expression of D2-40, WT-1, and mesothelin supported their mesothelial origin." (PMID 28545562, 2017). "Finally, an alternative hypothesis relies on the fact that WT1 is a key regulator of the epithelial/mesenchymal balance during development and therefore it may also play a role in the EMT of tumour cells." (PMID 28345629, 2017). "WT1 28z T cells were specific for the WT1-HLA-A*02:01 complex and the outcome provided the proof-of-concept that CAR T cells could not only target the protein expressed on the cell surface of the tumour, but also target at intracellular antigens." (PMID 28053197, 2017). "Furthermore, it was proposed that the wild-type WT1 plays oncogenic rather than tumor-suppressor functions in leukemogenesis and tumorigenesis." (PMID 26090994, 2015). "One could argue that these tumours are in effect the same as the WT1-mutant tumours, having no functional WT1 protein in combination with a CTNNB1 mutation." (PMID 26035382, 2015).
tumor (continued). "We electroporated these DCs either without RNA (mock) or with a panel of 16 different RNAs encoding tumor antigens, or parts thereof (MelanA, NRAS, BRAF, GNAQ, GNA11, and WT1), either mutated or not, and either linked to the lysosomal targeting signal DC-LAMP or not." (PMID 26824052, 2015). "Interestingly, in our tumor model we see increased expression of Ang1 and Tie2, in addition to VEGF, strengthening the hypothesis that WT1 is a more global regulator of angiogenesis." (PMID 24810959, 2014). "It is also not known whether the WT1 gene is a tumor suppressor gene or an oncogene, or whether it has a biphasic function." (PMID 25026998, 2014). "In a preliminary PET study involving 4 Wt1-Igf2 mice, delayed acquisition of PET images up to 3 h post 18F-FDG administration resulted in a significant clearance of 18F-FDG from the kidneys and “unmasking” of areas or radioactivity accumulation in the tumor tissue." (PMID 22875335, 2013). "Importantly, WT1 protein expression was demonstrated in tumor tissues and was absent in normal and benign tissues." (PMID 20426842, 2010). "Although the precise histologic composition of tumours in the present study was unknown, whether or not there is a correlation between the WT1 expression reduction and histology is not clear because the number of tumours was small." (PMID 16909133, 2006). "This may result from intratumoral heterogeneity – demonstrated, for example, by the variable expression of WT1 in HGSC_3, and also CK7 in SBT/LGSC_1 – coupled with selection pressure within the culture, induced by media composition, thus favouring specific tumour subpopulations." (PMID 40835947, 2025). "Similarly, our case showed focal positivity for both CD34 and S100, while additional immunoreactivity may be present but is less specific for this type of neoplasm (e.g., WT1, CD10, desmin, and smooth muscle actin; not shown)." (PMID 39582973, 2024). "Additionally, our data indicate that 1) WT1-specific CTL frequency was significantly greater (p < 0.05) in the B. longum 420/2656 combination group than in the B. longum 420 group and 2) WT1-specific CTL frequency in CD8+ T cells in PB was inversely correlated with tumor volume." (PMID 36803483, 2023). "Additionally, Cytokeratin 7 and 20, CD56, synaptophysin, chromogranin, SF1, α-inhibin, WT1, desmin, SMA, GATA3, Uroplakin II, CD10, PR, CD5, BerEP4, and NUT were negative in tumor cells, no loss of INI1 expression, β-catenin showed only membranous staining without nuclear accumulation (no shown)." (PMID 37518334, 2023). "However, WT1 is not expressed in the M4 cell line (primary tumor with WT1 expression)." (PMID 37621847, 2023). "However, if the WT1-332 peptide strongly induces immunosuppressive IL-10 production/secretion by HTLs, it may have a negative impact on the anti-tumor immune responses." (PMID 36672344, 2023). "Moreover, TNM staging also did not seem to relate to WT1 protein expression, seeing as most positive cases were pT1a/b (localized tumors, <7 cm) and the only pT3a (invasion of renal sinus fat) WT1positive tumor had <10% of tumor cells positive for WT1." (PMID 35453662, 2022). "In a sporadic WT1 mutation case the first mutation occurs in a specific kidney cell, likely followed by a CTNNB1 mutation in the same cell, but this cell might not form a tumor." (PMID 33379206, 2020). "In the current study, WT1 expression was lower than what has been reported in most papers in the recent literature, which might be explained by the irregular staining of tissue for WT1, additionally, the TMAs used may not contain the most immunoreactivity areas of the tumours." (PMID 29662608, 2018). "Moreover, we evaluated the expression of Ron isoforms in 3 of our newly developed HG-SOC PDX tumor models, which have also been immunohistochemically characterized for the expression of commonly used markers for HG-SOC subtype such as pan-cytokeratin (CK), PAX8 and WT1." (PMID 27551332, 2016).